CD86 (CD86 molecule)
Diseases named in the same sentence as CD86 in open-access papers (continued):
Sharing a sentence is not in itself a finding about the gene and the disease.
Autoimmunity (31 papers, 2005 to 2025). The occurrence of an immune reaction against the organism's own cells or tissues. "These individuals suffer from a variety of autoimmune features and we show in the present study that patient-derived CTLA-4 Arg70Gln mutations associated with autoimmunity lose the ability to transendocytose CD86." (PMID 35999394, 2022). "Data herein clearly show that DN B cells from individuals with obesity express higher levels of membrane markers of IA associated with autoimmunity as compared to lean controls and are characterized by the phenotype CD21lowCD95+CD11c+CD86+HLADR+PD1+." (PMID 33708209, 2021). "In DKO* mice, LCs within the epidermis as well as in lymph nodes exhibited higher levels of CD205, PD-L1, and CD86, which have been associated with DC-mediated generation of regulatory T cells, peripheral T-cell tolerance, and protection from spontaneous autoimmunity." (PMID 25216727, 2014). "CD86 (T-lymphocyte activation antigen CD86) is the costimulatory molecule on antigen-presenting cells, playing an important role in autoimmunity and tumor immunity." (PMID 37726845, 2023). "In the nonobese diabetic (NOD) mouse model, wherein CD28 or its ligands (CD80 [B7-1] and CD86 [B7-2]) have been knocked out, the number of natural Tregs (nTregs) decreased significantly, resulting in accelerated autoimmunity in mice." (PMID 37828948, 2023). "Abatacept, on the other hand, directly targets B cells by decreasing the expression of CD80/CD86, thereby offering a potential therapeutic approach for treating B cell-mediated autoimmunity." (PMID 38041172, 2023). "CD69 has been identified as a B cell marker associated with MS whereas CD80 and CD86 are costimulatory molecules that are involved in immune regulation and B cells expressing CD80/CD86 have been shown to drive pathogenesis in autoimmunity." (PMID 36389698, 2022). "In several NSCLC cells, the mRNA expression of CD80/CD86 was detected in normal tissues, risking autoimmunity reactions; hence, new strategies are encouraged to overcome this risk by using CD80/CD86 CAR-T cells and enhancing its selectivity." (PMID 35814023, 2022). "CaMK4 is responsible for regulation of CD86 in podocytes, along with other cytokines that are key players in autoimmunity." (PMID 33784256, 2021). "Pretreatment of THP-1 cell lines with sera from autoimmune patients characterized by the presence of sCTLA-4 led to a significant reduction of staining by anti-CD86 mAb (12AIT, 26CD, and 31PBC)." (PMID 24605322, 2014). "We conclude that the major mechanism used by Treg in the steady state is the regulation of CD80/CD86 expression and dysregulation of this suppressor pathway results in lethal autoimmunity driven by co‐stimulatory signals in concert with TCR stimulation, or even by costimulatory signals alone." (PMID 40346769, 2025). "Animal studies suggest that Tet2- and Tet3-mediated chromatin modification participated in the repression of CD86 on self-reactive B cells, a mechanism that may contribute to autoimmunity prevention." (PMID 37048133, 2023). "Additionally, given that CD86 overexpression in tolerant B cells caused them to break tolerance, collectively, Tet2 and Tet3 are essential for CD86 expression suppression in self-tolerant B cells and play important roles in autoimmunity prevention." (PMID 34222235, 2021). "Abatacept inhibits the CD80/CD86:CD28 costimulatory signal required for full T cell activation and as such may alter the immune responses to tumors, as well as dampening pathogenic autoimmunity." (PMID 31703717, 2019). "B cell-expressed CD80/CD86 has been shown to drive pathogenesis in autoimmunity." (PMID 24472094, 2014). "The remarkable therapeutic efficacy of anti‐CD80/CD86 mAbs in preventing immune activation post‐Treg depletion raised the possibility that blockade of the delivery of co‐stimulatory signals may be used to treat ongoing autoimmunity secondary to complete deletion of Treg or dysfunctional Treg." (PMID 40346769, 2025).
Autoimmunity (continued). "Other studies reported that DT-mediated depletion of Foxp3+ cells in DEREG mice induced increased division of DC and precursor DC in lymphoid organs and up-regulation of CD80, CD86 and CD40 in the context of autoimmunity." (PMID 36846549, 2022). "Consistently, ablation of B7/CD28 signalling in CD80/CD86 knock-out mice or clinically with CTLA-4Ig (abatacept) has been shown to impair T cell regulation and lead to aggressive secondary autoimmunity." (PMID 32580776, 2020). "The CTLA-4 receptor is located on the surface of effector T lymphocytes and interacts with CD80/CD86 (B7-1 or B7-2) on CTLA-4 antigen-presenting cells to induce T cell rest, preventing overactivation of the T cell system in autoimmunity." (PMID 28977985, 2017). "Despite their largely overlapping functions in T cell activation and immune upregulation in autoimmunity, CD80 and CD86 on APCs also play additional individually distinct roles, which cannot be substituted for by the other." (PMID 24472094, 2014). "In addition, CD21lo B cells derived from patients with autoimmunity can serve as antigen presenting cells, as these cells express high levels of CD80, CD86 and HLA-DR." (PMID 36591307, 2022). "It has been suggested that CD86 is more important than CD80 in mediating resting T-cell activation by APCs and is essential for autoreactive T-cell activation and development for autoimmunity." (PMID 26209442, 2015). "It has been demonstrated that the expression of MHC molecules and the expression of costimulatory molecules such as B7-1 (CD80) and B7-2 (CD86) could modulate T cell activation and Th1/Th2 polarization during infection and autoimmunity." (PMID 23533995, 2013). "Similarly, we also observed an increase in HLA-DR expression along with co-stimulatory molecules CD80 and CD86 in stimulated pDCs, suggesting that pDCs can efficiently present antigens to CD4 + T cells during autoimmunity and may contribute to the pathogenesis of T1D." (PMID 32483133, 2020).
myeloma (31 papers, 2014 to 2025). "Besides, CD86 expression was observed to be associated with unfavorable prognosis in myeloma and leukemia." (PMID 33954112, 2021). "The expression of CD86 was associated with poor prognosis in myeloma and leukemia." (PMID 33425732, 2020). "Myeloma cells expressing CD86 and CD28 can likely activate each other, promoting their survival and reducing their dependence on the microenvironment." (PMID 40635602, 2025). "This theory is further reinforced by the fact that Jurkat T cell line JE6.1 consistently express CD28 receptor and the multiple myeloma cell line, MM.1s expresses CD86 (B7-2) ligand." (PMID 40821776, 2025). "In particular, high expression levels of CD28 and CD86 have been identified as poor prognostic markers in myeloma patients, indicating their crucial role in disease survival and progression mechanisms." (PMID 38831187, 2024). "Tumor-associated neutrophils are known to express checkpoint inhibitory molecules such as PD-L1 and CD86 that can directly inhibit T cells, and a dysfunctional neutrophil profile has been detected in patients with multiple myeloma." (PMID 36874402, 2022). "Knockout of CD28 leads to decreased antibody titers of long-lived plasma cells in mice, and knockdown of CD28 or CD86 with short hairpin RNA leads to myeloma cell death in HMCL." (PMID 33634031, 2020). "Similarily, the CD28 receptor on multiple myeloma cells promote survival following interaction with its ligand CD80/CD86 on dendritic cells that is related to PI3K activation and Bim downregulation." (PMID 26405162, 2015). "In their studies, different populations of MM cells were distinguished by their CD45 expression: primitive (CD38hiCD45hi) and immature (CD38hiCD45lo) myeloma cells had higher CD86 levels than mature (CD38hiCD45neg) myeloma cells, while patients with mature myeloma cells had poorer prognoses." (PMID 40635602, 2025). "Besides dysfunctional CD8+ T-cells, tumor-associated macrophages (CD68+, CD163+, CD86−) and inactivated DCs (CD58−) are also found co-localized with myeloma cells, participating as well in the orchestration of an immunosuppressive state." (PMID 40227595, 2025). "Surprisingly, they found that CD86 is often co‐expressed with CD28 on myeloma cells." (PMID 40635602, 2025). "Moreover, the cytoplasmic region of CD86 is important for triggering molecular changes, such as the upregulation of Interferon regulatory factor 4 and Integrin beta-1 in myeloma cells." (PMID 38251379, 2024). "Our study results, when evaluated together with previous study results, suggest that CD86 may be an alternative for the treatment of myeloma cells with MYXV." (PMID 38251379, 2024). "Since we have shown that CD28 itself is important in myeloma progression and survival, this CD28/CD86 axis may represent a possible mechanism by which cis-interactions in the myeloma cell microenvironment may facilitate survival and disease progression." (PMID 32751699, 2020). "Prior studies have confirmed that U266 and primary myeloma cells express B cell membrane markers, including high levels of CD86 and CD54 and detectable levels of HLA-DR, CD40 and CD80, which can be upregulated by IFN-γ combined with microbial Ags or by BCGV alone." (PMID 31870332, 2019). "Interruption of the CD28-CD80/CD86 interaction sensitized multiple myeloma cells to chemotherapy." (PMID 26405162, 2015). "In eight of these, we examined 12 surface markers commonly used in myeloma research, while in four cases we studied only a subset of them (CD38, CD44, CD45, CD49d, CD69, CD86, CD138, and CD184)." (PMID 39493694, 2024). "Activation of CD28 on multiple myeloma (MM) plasma cells, by binding to CD80 and CD86 on dendritic cells, decreases proteasome subunit expression in the tumor cells and thereby helps them evade being killed by CD8+ T cells." (PMID 38654298, 2024). "A mechanism for myeloma autocrine pro-survival loop lies in the co-expression of CD28 and its ligand CD86." (PMID 33634031, 2020).
myeloma (continued). "CD86, which is the cognate ligand for the prototypic T cell co-stimulatory molecule CD28, is expressed by myeloma cells and is required for their survival." (PMID 32751699, 2020). "With CD86 blockade, three of the four patients had reduced entry of MYXV into myeloma cells." (PMID 38251379, 2024). "Considering the different roles of CD86 in different tumors, for example, infiltration of CD86 TAMs indicates a good prognosis in colorectal cancer, whereas in patients with multiple myeloma, CD86 TAMs do not correlate with tumor progression." (PMID 38611749, 2024). "Other B7 co-inhibitory ligands, such as CD86, CD80, and HHLA2, showed high expression levels in myeloma cell lines relative to the other cancer cell lines, implying that these B7 ligands might serve as potential targets for immune checkpoint therapy." (PMID 34504297, 2021). "CD86 overexpression induces molecular changes such as increased expression of integrin ß1 and ß7 and interferon regulatory factor 4 (IRF4), a transcription factor necessary for myeloma survival which directly targets MYC." (PMID 33634031, 2020). "Both the APC parent (HMy2) and the hybrid cell lines expressed CD80, CD86, and HLA class II, though they were consistently absent in the myeloma cell line U266." (PMID 31428094, 2019). "Moreover, their in vitro study on isolated myeloma cells showed that adding CD40L did not increase CD86 protein levels." (PMID 40635602, 2025). "Importantly for stimulation of T cell responses, levels of expression of MHC class I and class II were significantly higher, and the T cell costimulatory molecules CD80 and CD86, which were not expressed by the myeloma cell line U266, were expressed on the hybrid cell lines." (PMID 31428094, 2019). "Similarly, the multiple myeloma cell line, RPMI8226 also found to be CTLA4-FasL resistant, expresses only low surface levels of Fas and CD86, with no CD80." (PMID 25227919, 2014).
diabetes (29 papers, 2006 to 2026). "For example, diabetes resistance loci were introduced in NOD.CD86-/- mice to generate NOD.CD86-/–Idd3/5 and NOD.CD86-/–Idd3/10/18 congenic mice." (PMID 35572553, 2022). "First, spontaneous diabetes incidence is increased to 100% and disease onset is accelerated in NOD mice deficient in either CD28 or CD80 and CD86 that is directly correlated with a quantitative decrease in Tregs by >80%." (PMID 31281853, 2019). "The expression levels of HLA-DR, CD80, and CD86 were low while those of of PD-L1 were high in uninfected MDMs derived from patients with diabetes; as a result of Mtb infection, changes were only observed in the expression levels of PD-L1." (PMID 29513874, 2018). "This conclusion agrees with the result that blocking CD86 prevents the development of diabetes in NOD mice." (PMID 27699180, 2016). "REDD1 ablation prevented the diabetes-induced increase in CD86 + M1 macrophages." (PMID 39920111, 2025). "Interestingly, NOD.ICOS-/-, NOD.ICOSL-/-, and NOD.CD86-/- mice are all protected from diabetes, suggesting an important role for these costimulatory pathways in autoimmune diabetes." (PMID 35572553, 2022). "Furthermore, CRAMP treatment inhibited increases in the ratio of inflammatory macrophages (M1 MΦ) versus regulatory macrophages (M2 MΦ) and the frequency of CD86+ cDCs in C. rodentium-accelerated diabetes." (PMID 35547774, 2022). "As the basal expression of molecules important in macrophage activation has not been previously reported in patients with diabetes, we evaluated the expression of HLA-DR, CD80, CD86, and PD-L1 in MDMs derived from patients with diabetes compared to that in MDMs derived from healthy subjects." (PMID 29513874, 2018). "Eight studies investigated monocytes/macrophages in the liver under diabetes, using nine markers to identify monocytes/macrophages in mice (CD11b, Ly6C, F4/80, CD11c, CD206, and CD86) and humans (CD14, CD16, and CD68) at protein or RNA levels." (PMID 40362271, 2025). "Our results suggest that CD163+ monocyte-mediated T cell activation was down-regulated in individuals with diabetes-related complications, due to the increased CD5 and decreased CD86 expression." (PMID 39337580, 2024). "↑Serum insulin level, Th2-bias ed. cytokine response; ↓Onset and the development of diabetes, Th1 pro-inflammatory cytokines levels, MHC class II and CD86, TLR4 and downstream molecules’ expression in the pancreas." (PMID 37396125, 2023). "We also analyzed the mean fluorescence intensity (MFI) of these molecules and found that diabetes enhanced the MFI of CD80 and CD86 on B cells in EAMG rats." (PMID 34702288, 2021). "Previous experiments with adoptive transfers of mature bone-marrow derived DCs expressing high levels of co-stimulatory molecules, such as CD80, CD86 and CD40, significantly reduced diabetes incidence in NOD mice." (PMID 25166904, 2014). "On the other hand, the development of diabetes in NOD mice, a model for insulin-dependent diabetes mellitus (IDDM), is exacerbated by treatment with anti-CD80 mAb and is blocked by treatment with anti-CD86 mAb." (PMID 22997525, 2012). "Previous reports have shown that IFN-α can induce the expression of CD86 and ICAM-1 in murine Mac-1 monocytes/macrophages in a model of diabetes induction in vivo." (PMID 18588665, 2008). "Flow cytometric characterization of macrophage polarization states revealed a significantly increased M1/M2 ratio (CD86+/CD206+) in HFD + STZ atrial tissue versus controls, demonstrating diabetes-induced polarization toward pro-inflammatory M1 macrophages in atrial tissue." (PMID 41356195, 2026). "Downregulated CD86 expression on MZB cells was also observed in the spleen and pancreatic lymph nodes of HAMSA-fed NOD mice in which reduction of hyperactive antigen-presenting MZB cells correlated with protection against diabetes." (PMID 35045871, 2022).
diabetes (continued). "Differentially regulated genes not overlapping with ERCB data also reflected diabetes-associated changes, such as extracellular matrix (ANGPTL4, TNN, DPT, COL9A2) or gestational diabetes (LAT2, HP, CXCL10, CD86, CD68, REN, SLC2A3, VCAM1)." (PMID 33923831, 2021). "Diabetes promoted B cell activation and upregulated the expression of CD80 and CD86, which may account for the differentiation of CD4+ T cells from Treg cells towards Th1/Th17 cells." (PMID 34702288, 2021). "In this study, senescence markers (such as P16INK4a), inflammatory macrophage phenotypes (CD86, CD163, MCP-1), and immunometabolic enzymes (SDH, ACLY) were evaluated as downstream mechanistic responses to DN rather than as diagnostic criteria for diabetes or DN themselves." (PMID 41471323, 2025).
lung carcinoma (29 papers, 2011 to 2025). "Whereas macrophages from both lung cancer patients and healthy donors expressed similar levels of CD86, the former had stronger CD206." (PMID 29484139, 2018). "In summary, we show that a balance of HO-1 and CD86 expressions in myeloid cells in response to CO treatment is critical for host responses during progression of lung cancer." (PMID 26993595, 2016). "In addition, sanguinarine could also induce accumulation of H3K4me2/H3K9me2 and CD86 in the lung cancer cells and suppress cell growth." (PMID 35949313, 2022). "Subsequently, flow cytometric analysis was performed to quantify the expression levels of CD86 and CD206, which respectively serve as specific surface markers for M1 and M2 macrophage subtypes, in TAMs derived from the lung cancer co‐culture system." (PMID 41328768, 2025). "In fact, DCs cultivated in the presence of lung cancer patient serum have shown decreased expression of CD40, CD80, CD86, MHCII, IL1 and NFκb, similarly to the results we showed here." (PMID 34535708, 2021). "DC-based HHP lung cancer vaccine [HHP+poly(I:C)] displays significantly higher expression of CD80, CD83, HLA-DR and CD86 than control immature DC [iDC], DC pulsed with HHP-killed cells alone [HHP] or DC stimulated only with poly(I:C) [poly(I:C)]." (PMID 28187172, 2017). "In the early stages of lung cancer, crosstalk between TANs and activated T cells resulted in significant upregulation of CD54, CD86, OX40L, and 4-1BBL co-stimulatory molecules on the surface of neutrophils, which promoted T cell proliferation in a positive feedback loop." (PMID 40160822, 2025). "In addition, we found that endurance exercise significantly decreased the mRNA levels of CD86, TNF-α, and iNOS in lung cancer tissues." (PMID 36186906, 2022). "It was also found that platinum-containing drug oxaliplatin induced immunogenic cell death (ICD) in LLC cells, activating dendritic cells with CD80+CD86+ phenotype and enhancing cytotoxic CD8+ T cells in LLC tumor tissues, which resulted in tumor regression in a mouse model of lung cancer." (PMID 33194645, 2020). "We observed that co-injection of A549 lung carcinoma cells with non-polarized or M2-polarized (MMR-positive) macrophages slowed down tumor growth unlike when co-injected with M1-like (CD86/CD197-postive) macrophages." (PMID 26993595, 2016). "Notably, exosomes derived from Rab27a‐overexpressing lung cancer cells not only promote upregulation of MHC class II, CD80, and CD86 on DCs, but also facilitate CD4+ T cell proliferation and type I cytokine secretion, culminating in effective tumor growth inhibition in vivo." (PMID 41256221, 2025). "We found that although HIIT did not down-regulate the mRNA level of CD86, it significantly down-regulated the mRNA levels of IL-6, TNF-α, and iNOS in lung cancer tissues, which also functions as an anti-inflammatory role." (PMID 36186906, 2022).